CASC18 (cancer susceptibility 18)
Synonyms: LOC101929110
Gene: Long non-coding RNA gene on chromosome 12 (105,704,203 to 105,744,062, forward strand). Ensembl gene ENSG00000257859.
Diseases named in the same sentence as CASC18 in open-access papers:
CASC18 is named in the same sentence as 5 diseases in open-access papers, as found by Europe PMC text mining. Sharing a sentence is not in itself a finding about the gene and the disease. The quoted sentences say what the papers report.
COVID-19 (1 paper, 2021). A disease caused by infection with severe acute respiratory syndrome coronavirus 2. "Interestingly we found six lncRNAs (TALAM1, DLEU2, and UICLM CASC18, SNHG20, and GNAS) involved in the protein-coding DEG-lncRNA network; which might be served as potential biomarkers for COVID-19 patients." (PMID 34975833, 2021).
cancer (2 papers, 2018 to 2021). A tumor composed of atypical neoplastic, often pleomorphic cells that invade other tissues. "The cancer susceptibility candidate 18, CASC18, is a lncRNA in a cancer predisposition locus at 12q23.3 and was recently cloned as 4 splice variants (A, B, C, and D)." (PMID 29351317, 2018). "Although CASC18 named as Cancer Susceptibility 18, this gene was previously reported involved in neural cell differentiation and oocyte growth, instead of cancer." (PMID 34362313, 2021).
tumor (2 papers, 2021 to 2025). "Meanwhile, we noticed that CASC15, CASC8, CASC9, and CASC19 were highly expressed in tumor samples and CASC16 and CASC18 were lowly expressed in tumor tissues." (PMID 40746360, 2025). "CASC18 was identified up-regulating in TSCC tumours, and especially in those from patients with OLNM." (PMID 34362313, 2021). "In TCGA-TSCC cohort, the significantly lower level of CASC18 expression was detected in normal tongue tissues when compared with TSCC (p = 0.007) but also corresponding tumor tissues (p = 0.040), respectively." (PMID 34362313, 2021). "We found CASC18 is a prognosis factor up-regulated in tumour samples and especially in those of TSCC patients with OLNM, partly supporting the roles of CASC18 in lymph node metastases." (PMID 34362313, 2021).
CASC18 also shares sentences with these, for which no sentence is quoted: lymph node metastasis (1 paper); tongue squamous cell carcinoma (1).